COL1A1 (collagen type I alpha 1 chain)
Diseases named in the same sentence as COL1A1 in open-access papers (continued):
Sharing a sentence is not in itself a finding about the gene and the disease.
tumor (continued). "Col1a1-driven-specific ATF4 deletion caused a significant growth delay in B16F10 tumours, similar to that observed in Atf4Δ/Δ mice." (PMID 35654839, 2022). "Researchers found that COL1A1 expression was significantly upregulated in tumor tissues and was significantly associated with clinical outcome." (PMID 33969120, 2021). "Meanwhile, COL1A1 expression exhibited a significant association with tumor purity, CD4 T cells, macrophages, and neutrophils." (PMID 33490271, 2021). "High expression of the COL1A1 gene will cause unrestricted growth factors which, in turn, will benefit tumor proliferation." (PMID 33758613, 2021). "The UV–GFP+ population was sorted as tumor-associated Col1a1-expressing cells and submitted for scRNAseq analysis." (PMID 33173221, 2020). "COL1A1, a fibrillar collagen encoding gene found in the stroma of multiple cancers, plays a role in tumour proliferation, invasion, migration and angiogenesis." (PMID 31959771, 2020). "Many over-expressed genes in tumor-associated T cells were involved in tissue remodeling (e.g., Col1a1, Col4a1, Fn1, Lamc1, Mmp2, Mmp10, Timp3) and cell motility/adhesion (Rhoc, Itga1, Itgav)." (PMID 31477729, 2019). "COL1A1 encodes the major component of fibrillar collagen found in most connective tissues, and involved in gap junction, cell proliferation and tumor invasion." (PMID 30068360, 2018). "The results indicated that high COL1A1 expression was significantly associated with poor prognosis in tumor subgroups with enriched B cells (HR=1.43, p=0.04), as well as in cohorts with enriched macrophages (HR=1.54, p=0.016) and decreased macrophages(HR=1.57, p=0.046)." (PMID 39845977, 2024). "Col1A1+ tumor-associated endothelial cells promote angiogenesis and neovascularization in PDAC." (PMID 38546390, 2024). "COL1A1 has been recognized as a potential prognostic molecular marker in various cancers, such as mesothelioma and lung cancer, and is associated with the presence of tumor-infiltrating immune cells." (PMID 39845977, 2024). "Similarly, in our patient cohort, higher expression of COL1A1 was detected in tumour samples, and it was associated with poor OS and RFS." (PMID 37496319, 2023). "Inhibition of Col1a1 eliminates oncostreams, reprograms the malignant histopathological phenotype, reduces expression of the mesenchymal associated genes, induces changes in the tumor microenvironment and prolongs animal survival." (PMID 35750880, 2022). "Collagens (fibrillar forming collagen COL1A1 encodes the proalpha 1 chains of type I collagen whose triple helix comprises two alpha 1 chains and one alpha 2 chain), found in most connective tissues, are involved in tumor invasion and progression." (PMID 34943943, 2021). "Additionally, tumour associated macrophages of monocyte origin were shown to upregulate COL1A1 directly, affecting collagenous matrix organisation in the tumour microenvironment." (PMID 34867934, 2021). "In addition, the study shows that COL1A1 expression is closely related with tumor purity and linked to CD4+ T cells, Macrophage, Neutrophil and Dendritic cell in LUAD and LUSC." (PMID 33850663, 2021). "Notably, elevated expression collagen-associated genes, including COL10A1 and COL1A1, was observed in tumor tissues when compared to normal tissues." (PMID 34758833, 2021). "Besides, we explored the correlation of COL1A1 with cancer prognosis, immune infiltrates, PD-L1, tumor mutational burden (TMB)/microsatellite instability status (MSI), and the pathway and drug sensitivity of co-expressed genes." (PMID 34395525, 2021). "COL1A1 is associated with response to hypoxia and oxidative stress, which may help the cells adapt to oxidative stress and hypoxia, thus promoting tumor cell growth and metastasis." (PMID 34475986, 2021). "In addition, our study shows that increases in COL1A1 expression often occurred later in tumor progression and is associated metastasis to the lymph nodes." (PMID 33062455, 2020).
tumor (continued). "As is well-known, COL1A1 is expressed in many tumor cells and tumor-associated stromal cells." (PMID 25887589, 2015). "Using the reads mapping to the transcript encoding for the reporter (dsRED) we selectively identified the tumor cells, which we found to express a mesenchymal signature of transcripts encoding for extracellular matrix genes and collagens (Col1a1, Col1a2, Cald1, Calu)." (PMID 38509063, 2024). "Moreover, a series of key bacteria and bacteria-gene association pairs were screened out based on bioinformatic analysis, such as the tumor-promoting bacteria Fusobacterium, the tumor-suppressing bacteria Actinomyces, and the significant Rhodopseudomonas-COL1A1 association pair." (PMID 39924716, 2024). "In view of the strongly association between COL1A1 expression and prognosis in lung tumor, we theorized that COL1A1 expression may be regulated by inflammatory responses, contributing to affect the survival rates of tumor patients." (PMID 33850663, 2021). "Besides, the expression of COL1A1 was associated with the TAX resistance of tumours and could be affected by the autophagy level in OC cell line." (PMID 32319226, 2020). "Collagen is one of the important components in the tumor microenvironment, the experimental results of subtractive hybridization and microarray indicated a variety of collagen genes that were abnormally expressed in tumor tissues, such as COL1A1 encoding type 1 collagen." (PMID 25860484, 2015). "We conclude that the overexpression of Col1a1 may suppress the transformed phenotype, whereas the downregulation of Col1a1 mediated by the codon 12 Kras mutation contributes to the neoplastic phenotype with the ability of tumour cells to metastasise." (PMID 19190631, 2009). "Hence, while limitations of the model must be taken into account when considering the presented data, it appears unlikely that a defect in matrix remodeling associated with the use of the Col1a1 model is causal for the increases in tumor formation and progression observed in this study." (PMID 18442412, 2008). "Transcriptomic analysis revealed that ADX downregulated tumor-induced transcripts in bone by over 90%, including osteogenic (Lox, Sparcl1, Bmp2, Postn, and Col1a1) and pro-angiogenic (Bmper, Pecam-1, and Esam) signatures." (PMID 42149634, 2026). "The differential proline hydroxylation of COL1A1 in benign versus malignant tumors also implicates potential differences in the hypoxia signaling pathways between these tumor types." (PMID 40216311, 2025). "Knockdown of COL1A1 inhibited tumor cell proliferation, migration, and invasion in both in vitro and xenograft models, as well as suppression of epithelial-mesenchymal transition (EMT)." (PMID 40851082, 2025). "In line with this, patient tumor datasets revealed an inverse correlation between COL1A1 expression and CD8+ T cell infiltration, and the survival benefit associated with high CD8+ T cell levels was only observed in tumors with low collagen expression." (PMID 40847444, 2025). "These FOXL2+ cells in the COL1A1+ regions frequently co-stained with other tumor markers from our IMC panel, including SF1, calretinin, and inhibinα." (PMID 41042551, 2025). "Three type VI COLs (encoded by COL6A1, COL6A2, and COL6A3) and two type I COLs (encoded by COL1A1 and COL1A2) constituted a significant proportion of the human colon ECM in NAT (55.6%) and tumor (31.8%) tissues." (PMID 40032993, 2025). "The first subgroup of FOXL2+COL1A1+ cells expressed other tumor markers (expression profiles highlighted by frames 1 and 2)." (PMID 41042551, 2025). "Immunohistochemical analysis revealed elevated H scores for CDK1, STAT1, COL1A2, and COL1A1 in tumor tissues." (PMID 39911265, 2025). "On the other hand, in myCAF, relatively up-regulated gene is collagen type 1α1 (COL1A1), which plays an essential role in inducing the differentiation and metastasis of cancer cells and promotes tumor infiltration." (PMID 41376815, 2025).
tumor (continued). "Four primary cell populations were first identified using canonical cell markers: WT tumor cells (WT1, NCAM1, SIX1, SIX2, PAX2), cancer-associated fibroblasts (CAFs) (ACTA2, TAGLN, COL1A1, PDGFRB), endothelial cells (PECAM1, CLDN5, ENG, VWF) and immune cells." (PMID 40098972, 2025). "COL1A1 is involved not only in tumor drug sensitivity but also in the epithelial-mesenchymal transition (EMT), a key process in cancer progression." (PMID 40851082, 2025). "Collagen proteins (COL1A1, COL1A2, COL3A1, COL11A1) were associated with tumor progression and metastasis." (PMID 40867231, 2025). "The persistent upregulation of COL1A1 reinforces the idea of an evolving fibrotic and pro-migratory microenvironment in response to tumour-derived signals." (PMID 40282535, 2025). "Enlarged cells remodel the tumour microenvironment by secreting more collagen (COL1A1) and matrix metalloproteinases (MMPs), facilitating tumour invasion and migration." (PMID 40525649, 2025). "CAF1 has features of the COL1A1-expressing CAF type known to restrict tumour growth and is most likely related to wound healing in this context." (PMID 40640495, 2025). "This study identifies COL1A1, ITGB1, THY1, and PDGFRA as crucial regulators of UCEC progression, with altered expression linked to tumor behavior and patient survival." (PMID 40817072, 2025). "On one hand, they extensively synthesize and deposit extracellular matrix components, represented by COL1A1, to construct a fibrotic microenvironment that promotes tumor invasion and metastasis." (PMID 41099090, 2025). "Recent data obtained dissecting ovarian CAF populations by ATAC and scRNA seq analysis revealed that the myCAF cluster containing COL1A1 and FN1 is the most critical for tumor growth and metastasis, associated with short-term survival." (PMID 39985042, 2025). "We found that the EDEM3 expression in epithelial cells (marked by KRT18, EPCAM, KRT8) was significantly higher in tumour tissues with a large proportion of CAFs (marked by COL1A1, COL1A2, COL6A1, COL6A2) in the GSE188711 CRC dataset." (PMID 39754316, 2025). "We noted that endothelial cells, CD8 T cells, M2 macrophages, COL1A1+ cells, and COL1A1+αSMA+ cells were most strongly avoidant of FOXL2+COL1A1− tumor cells." (PMID 41042551, 2025). "Interactions with tissue stem cells through the Col1a1/Cd93, Col1a1/Itga5, Fn1/Plaur and Itgb1/Vcan pathways underscore the critical role of the monocyte-macrophage system in tumour immunosurveillance and immunomodulation." (PMID 40046334, 2025). "Of note, in both cases tumor-bearing bones displayed upregulated Col1a1 and Fn1 levels compared with non-tumor-bearing bones, suggesting that differential response is due to intrinsic characteristics of each model, possibly influenced by AR signaling status." (PMID 40753365, 2025). "The top 6 most abundant proteins encoded by COL6A1/2/3, COL1A1/2, and FBN1 detected in both NAT and tumor tissues and exhibited a similar trend in both composition and abundance." (PMID 40032993, 2025). "COL1A1, encoding type I collagen, is a critical component of the ECM, whose accumulation and remodeling within the tumor microenvironment contribute significantly to tumor metastasis and progression." (PMID 40851082, 2025). "In striking contrast to SASH1, the expression of COL1A1 clearly delineated the stromal architecture of the tumor." (PMID 41099090, 2025). "COL1A1, COL11A, and THBS1 are associated with tumor invasiveness and poor prognosis in ovarian cancer." (PMID 37322261, 2024). "Expression of collagen genes (e.g., COL1A1 and COL1A2) is induced in tumor stromal cells such as cancer-associated fibroblasts (CAFs) and in tumor cells by transforming growth factor beta 1 (TGFβ1)-mediated phosphorylated SMAD3 (pSMAD3) signaling." (PMID 39574893, 2024). "COL1A1 also modulates the efficacy of tumor treatments, such as chemotherapy, radiation, and immunotherapy, suggesting that COL1A1 plays a role in tumor development." (PMID 38195542, 2024).
tumor (continued). "Previous studies have reported that COL1A1 is overexpressed in a variety of cancers, and it is involved in a variety of tumor-related biological processes, including the regulation of cancer cell proliferation, migration, invasion and metastasis." (PMID 39845977, 2024). "COL1A1 promotes tumor cell proliferation, epithelial–mesenchymal transition, and metastasis by binding to its receptor." (PMID 38195542, 2024). "Studies have shown that COL1A1 is usually upregulated in cancer, and this abnormal expression is closely related to the regulation of tumor cell proliferation, differentiation and migration." (PMID 39845977, 2024). "In summary, our research highlights the significant overexpression of COL1A1 in OC and its crucial role in tumor metastasis, immune regulation, and prognosis." (PMID 39845977, 2024). "Overall, we found that the expression of COL1A1 in OC was significantly elevated and closely correlated with clinical features such as pathological stage of tumor and prognosis." (PMID 39845977, 2024). "COL1A1 showed particularly high fold changes in these subtypes, reinforcing its potential role in tumor aggressiveness and extracellular matrix remodeling." (PMID 39850811, 2024). "This strong concordance between microarray and qRT-PCR data for COL1A1 validates its reliability as a molecular marker, supporting its role in promoting tumor invasiveness in these more aggressive subtypes." (PMID 39850811, 2024). "The results of survival analysis and immunoinfiltration analysis showed that COL1A1 is closely related to tumor immune cells in OC." (PMID 39845977, 2024). "In TCGA cohorts, COL1A1 mRNA expression was significantly higher in tumor tissues than in adjacent normal tissues across various types of cancer." (PMID 39191749, 2024). "Through additional analysis of the TNMplot database, we assessed COL1A1 mRNA expression levels in normal tissues (n=46), tumor tissues (n=744), and metastatic OC tissues (n=44)." (PMID 39845977, 2024). "As a result, we found COL1A1 had a significantly higher expression level in tumor tissues than in normal ones, while miR-766-3p, conversely, had a significantly lower expression level in tumor tissues." (PMID 38230216, 2024). "Tumour-cell-derived Col1a1 has also been reported as a metastatic driver in breast and liver cancer models." (PMID 38791926, 2024). "Cell clusters obtained were characterized based on their gene expression profile and identified as B16F10 tumor cells (Pmel, Mlana), mT4 tumor cells (Krt18, Krt19), and fibroblasts (Col1a1, Dcn)." (PMID 38987547, 2024). "It acts as a barrier to early tumor invasion and can restrict cancer cell growth, as evidenced by studies where the deletion of the COL1A1 gene led to increased metastasis formation." (PMID 39273393, 2024). "LUM+ tumor cells were mainly enriched in proteoglycans in cancer and extracellular matrix organization and demonstrated expression of the MMP2, MMP14, COL1A1, COL6A2, and COL1A2 genes, associated with extracellular matrix remodeling." (PMID 39685635, 2024). "Simultaneously, there was a significant upregulation of MPZ and COL1A1 levels and a decrease in Ki‐67 levels in the tumor tissue treated with recombinant mRNA, demonstrating the acquisition of Schwann cell‐like characteristics within the tumor." (PMID 38973154, 2024). "Mice with Col1a1-dependent Ccn2 ablation bearing B16F10 tumors showed impaired expression of canonical CAF markers including aSMA with reduced tumor angiogenesis." (PMID 38525245, 2024). "All examined fibrotic markers α-SMA (Acta2), Col1A1, and Col4A1 and proliferation markers are also dramatically increased in the tumor." (PMID 39796711, 2024). "Col1a1 is overexpressed in GC, and its reduction following IL-11 Mutein treatment further suggests remodeling of the tumor matrix." (PMID 38542101, 2024).
tumor (continued). "Genes such as COL1A1, COL1A2, and COL3A1, which are implicated in the tumor microenvironment, and immune-related genes, such as THY1, IRF5, and HLA-DRA, exhibited significant expression level changes." (PMID 38672562, 2024). "The colocalization of TINAGL1 and COL1A1, a fibroblast marker, was observed and more pronounced in the tumor tissues." (PMID 38355577, 2024). "Analyzing experimental data from two groups, both KRT17 and COL1A1 mRNA were highly expressed in case tissues, which are also correlated with age, blood glucose and tumor size." (PMID 38979664, 2024). "Immunohistochemistry (IHC) staining of the subcutaneous tumours showed increased COL1A1, VDAV2, and EMT activation changes in the hsa_circ_0057105 overexpression group." (PMID 37496319, 2023). "Although collagen has been demonstrated to affect T cells in tumor microenvironment, the role of COL1A1 and COL3A1 in promoting the migration and activity of immune cells has yet to be explored." (PMID 37415178, 2023). "Because of the relationship with stroma fraction for COL1A1 and fibrillar collagens, ColClusters were ordered by stroma fraction with ColCluster 1 having the highest median stroma fraction in each tumor type." (PMID 37414817, 2023). "The expression of L-R gene pairs including COL1A2-SDC4, COL1A2-SDC1, COL6A1-SDC1, COL6A2-SDC1, and COL1A1-ITGA2_ITGB1 was higher in sender and receiver cells derived from tumor tissue compared with those from normal tissue." (PMID 38002057, 2023). "Previous findings have shown that down-regulation of COL1A1 can increase the expression of E-cadherin, enhance the adhesion between cells, maintain the epithelial cell matrix, accelerate the apoptosis of tumor cells, and inhibit the growth of tumors." (PMID 38045487, 2023). "COL1A1 influences the development and prognosis of various tumors by involvement in tumor cell metastasis, proliferation, and apoptosis." (PMID 36878975, 2023). "FISH utilizing the PDGFB break-apart probe revealed unbalanced translocation presenting additional 3’-red signals in 5% of these tumor cells, while the COL1A1-PDGFB fusion probe showed yellow signal denoting a fusion pattern in 2% of tumor cells." (PMID 36776313, 2023). "Consistently, our results herein showed that down-regulation of COL1A1 improved the tumor microenvironment and inhibited the activation of fibroblasts." (PMID 38045487, 2023). "In comparison to normal tissues, tumor tissues have significantly increased levels of COL1A1 and GOLM1 protein expression." (PMID 38001428, 2023). "Not only were many collagen genes overexpressed in tumor progression between T1 and T2 stages, but also the mRNA expression of these collagen genes, such as COL1A1, COL1A2, COL3A1, COL5A1, COL5A2, COL6A2, and COL6A3, was highly positively correlated." (PMID 36596829, 2023). "The mRNA levels of Col1a1 and the collagen content were decreased in the skin lesions of C. albicans-infected mice, indicating that the fibrotic features of the dermis were suppressed after infection." (PMID 38032898, 2023). "It has been reported that there is increased expression of COL1A1 in many tumors, which can participate in matrix remodeling and promote tumor invasion and distant metastasis." (PMID 38045487, 2023). "According to a study COL1A1, an important collagen type I component was overexpressed in a number of tumor tissues and increased metastasis in CRC85." (PMID 37816854, 2023). "Tumor-associated macrophages (TAMs) were identified by CD68, CD14, CD163 and HLA-DRA and cancer-associated fibroblasts (CAFs) were characterized by COL1A1, COL3A1, MMP2, and SPARC." (PMID 37007745, 2023). "Collagen such as COL1A1/COL1A2/COL3A1 can change the resistance of tumor cells by interacting with the ITGB1 integrin, as reported for other cancers." (PMID 36460803, 2023). "When 5-FU was treated alone or in combination with iRGD or/and 5-FU, CoL1a1 and CoL1a2 gene expression was significantly reduced in the tumor tissues (P<0.001)." (PMID 37396945, 2023).